HPCAL1 (hippocalcin like 1)
Description:
May be involved in the calcium-dependent regulation of rhodopsin phosphorylation.
Synonyms: VILIP-3; BDR1; HLP2
Tractability: PROTAC: ubiquitination databases record sites on it; its protein half-life has been measured.
Gene: Protein-coding gene on chromosome 2 (10,301,356 to 10,427,835, forward strand). Ensembl gene ENSG00000115756.
Subcellular location: Membrane
Gene Ontology:
Molecular function: protein binding; calcium ion binding
Biological process: regulation of signal transduction
Cellular component: membrane
Genetic constraint (gnomAD): Loss-of-function variants: 8 observed, 15.3 expected, observed/expected ratio (o/e) 0.52, 90% interval 0.31 to 0.94. The upper end of that interval is the gene's LOEUF score, 0.94, which puts it in group 4 of 6, group 1 being the genes least tolerant of losing a copy. Missense variants: 161 observed, 277.94 expected, observed/expected ratio (o/e) 0.58, 90% interval 0.51 to 0.66. Synonymous variants: 110 observed, 115.28 expected, observed/expected ratio (o/e) 0.95, 90% interval 0.82 to 1.12.
Homologues: Orthologues: chimpanzee HPCAL1 (99% identical), dog HPCAL1 (99% identical), guinea pig HPCAL1 (99% identical), macaque HPCAL1 (99% identical), pig HPCAL1 (99% identical), rabbit HPCAL1 (99% identical), mouse Hpcal1 (98% identical), rat Hpcal1 (98% identical), zebrafish hpcal1 (91% identical), tropical clawed frog hpcal1 (87% identical), Caenorhabditis elegans ncs-2 (49% identical), Drosophila melanogaster CG7646 (45% identical), and 2 more. Paralogues in human: HPCA (94% identical), NCALD (91% identical), VSNL1 (67% identical), HPCAL4 (66% identical), NCS1 (58% identical), RCVRN (51% identical), GUCA1B (45% identical), KCNIP1 (41% identical), KCNIP2 (41% identical), KCNIP3 (40% identical), GUCA1A (40% identical), KCNIP4 (39% identical), and 2 more.
Diseases named in the same sentence as HPCAL1 in open-access papers:
HPCAL1 is named in the same sentence as 35 diseases in open-access papers, as found by Europe PMC text mining. Sharing a sentence is not in itself a finding about the gene and the disease. The quoted sentences say what the papers report.
glioblastoma (6 papers, 2019 to 2025). The most malignant astrocytic tumor (WHO grade IV). "In addition, another marker gene for cluster 2, HPCAL1, promotes glioblastoma proliferation, which is a prevalent primary cancer with evident aggressiveness in the human brain." (PMID 38171928, 2023). "HPCAL1, a neuronal calcium sensor protein, was found to be upregulated by Ca2+ in glioblastoma (GBM) tissues and cells." (PMID 32282333, 2020). "HPCAL1 promotes tumor growth in NSCLC and promotes proliferation in glioblastoma, the latter occurring through activation of the Wnt/β-catenin signaling pathway." (PMID 40421217, 2025). "HPCAL1 also activates the Wnt/β‐catenin pathway by enhancing ERK stimulation and inhibiting GSK3β, thereby contributing to the proliferation of glioblastoma." (PMID 35645147, 2023).
hepatocellular carcinoma (5 papers, 2019 to 2025). A malignant tumor that arises from hepatocytes. "HPCAL1 is known to inhibit the growth of hepatocellular carcinoma cells by regulating cell cycle progression." (PMID 40585902, 2025). "HPCAL1 inhibits hepatocellular carcinoma progression by promoting p21 stabilization through the activation of the ERK1/2‐MAPK signaling pathway." (PMID 35645147, 2023). "Due to its downregulation in tissues and cells, HPCAL1 was recognized as a new suppressor gene for hepatocellular carcinoma (HCC) and was found to aggravate the clinical outcomes in HCC patients." (PMID 35645147, 2023).
pancreatic cancer (4 papers, 2011 to 2023). "Most genes have been related to diabetes and cancer, with most of them being linked to pancreatic cancer (CEACAM6, HDAC5, HPCAL1, PARVG, and STYXL1)." (PMID 36360783, 2022). "Inhibition of HPCAL1 inhibited pancreatic cancer progression and pancreatitis development in a mouse model, suggesting that targeted enhancement of HPCAL1 expression may be a potential antitumor strategy." (PMID 37794028, 2023). "Additionally, HPCAL1 is a serum marker for pancreatic cancer diagnosis, methylation changes in CNT‐induced lung cancer, and a highly plastic epigenetic marker of the early origin of prostate cancer." (PMID 35645147, 2023).
Alzheimer disease (3 papers, 2019 to 2025). A progressive, neurodegenerative disease characterized by loss of function and death of nerve cells in several areas of the brain leading to loss of cognitive function such as memory and language. "HPCAL1 was associated with Alzheimer's disease, autism, hypertension, coronary heart disease, chronic kidney disease, and enteropathogenic Escherichia coli infection." (PMID 35645147, 2023).
liver cancer (3 papers, 2019 to 2023). An epithelial or non-epithelial malignant neoplasm that arises from the liver. "Given that NAFLD is increasingly ranking the top risk factor for human liver cancer 54, dissecting the role and clinical relevance of HPCAL1 with NAFLD-associated HCC is of great significance for potential cancer subtyping and therapy." (PMID 36438486, 2022). "Clinically, we uncovered a negative association between HPCAL1 and mTOR signaling and lipid metabolic enzymes in human liver cancers." (PMID 36438486, 2022).
neuroblastoma (3 papers, 2019 to 2023). Neuroblastoma (NB) is the most common solid, extracranial childhood tumor. "Another study explained that certain PHOX2B variants are associated with neuroblastoma pathogenesis because of their inability to bind to key interacting proteins such as HPCAL1." (PMID 30889216, 2019). "A previous study found that neurite outgrowth can be eliminated by knocking down HPCAL1 expression in neuroblastoma cells." (PMID 35645147, 2023). "Elimination of the interaction by HPCAL1 knockdown with small hairpin RNA (shRNA) in the neuroblastoma cells with PHOX2B expression reduced the outgrowth of neurites." (PMID 30843345, 2019).
coronary heart disease (2 papers, 2023). "Besides having calcium-regulatory roles, HPCAL1 is strongly associated with myocardial infarction and coronary heart disease." (PMID 37443105, 2023).
glioma (2 papers, 2018 to 2019). A benign or malignant brain and spinal cord tumor that arises from glial cells (astrocytes, oligodendrocytes, ependymal cells). "We identified 20 GSC-upregulated miRNA-targeted genes associated with significantly reduced 5-year survival in GBM patients, including previously identified glioma-promoting genes HMGA2, MYO1C, RGS4, and several novel targets, such as HPCAL1, IMPDH1, and YWHAG (orange-colored genes)." (PMID 29587824, 2018).
cholangiocarcinoma (1 paper, 2023). A carcinoma that arises from the intrahepatic biliary tree (intrahepatic cholangiocarcinoma) or from the junction, or adjacent to the junction, of the right and left hepatic ducts (hilar cholangiocarcinoma). "However, our understanding of the HPCAL1 activity in cholangiocarcinoma (CCA) remains limited." (PMID 35645147, 2023).
colorectal cancer (1 paper, 2026). A primary or metastatic malignant neoplasm that affects the colon or rectum. "Furthermore, drug targeting experiments provide proof-of-principle evidence for promoting HPCAL1 as a therapeutic target for countering activated Wnt/β-catenin signaling in colorectal cancer." (PMID 42091587, 2026).
esophageal cancer (1 paper, 2025). A primary or metastatic malignant neoplasm involving the esophagus. "The results showed that COL4A1, DEK, GINS1, HPCAL1, KIF4A and RBMX were significantly increased in esophageal cancer tissues and decreased in the combined treatment group, suggesting that are potential prognostic markers." (PMID 41326355, 2025). "Decreased levels of COL4A1, DEK, GINS1, HPCAL1, KIF4A and RBMX predicted longer survival in esophageal cancer patients, while overexpression of IGFL1P1, LRRC57A-AS1, SNHG3, ULK3 and ZFYVE19 correlated with longer survival." (PMID 41326355, 2025).
idiopathic pulmonary fibrosis (1 paper, 2023). Idiopathic pulmonary fibrosis (IPF) is a nonneoplastic pulmonary disease that is characterized by the formation of scar tissue within the lungs in the absence of any known cause. "In this study, we identified four potential biomarkers (FHL2, HPCAL1, RNF182, and SLAIN1) and evaluated the potential pathogenic role of SLAIN1 in idiopathic pulmonary fibrosis." (PMID 37783761, 2023). "FHL2, HPCAL1, RNF182, and SLAIN1 were identified as biomarkers of idiopathic pulmonary fibrosis using LASSO logistic regression, RF, and SVM-RFE algorithms." (PMID 37783761, 2023). "In summary, this research successfully pinpointed four promising biomarkers (FHL2, HPCAL1, RNF182, and SLAIN1) and investigated the potential involvement of SLAIN1 in the pathogenesis of idiopathic pulmonary fibrosis." (PMID 37783761, 2023).
liver fibrosis (1 paper, 2025). "Moreover, studies on miRNAs have revealed that exosomal miR-342-3p derived from primary hepatic macrophages improves liver fibrosis by upregulating HPCAL1 (Hippocalcin-like protein 1) in HSCs, which subsequently inhibits TGF-β signalling." (PMID 40969268, 2025).
meningioma (1 paper, 2017). A generally slow growing tumor attached to the dura mater. "The HPCAL1, a neuronal calcium sensor protein which is found in brain, was found to generate significant autoantibody levels in meningioma patients." (PMID 28938569, 2017).
Nivelon-Nivelon-Mabille Syndrome (1 paper, 2022). "Of these, four genes were determined to be related to bone development (PLXNA2 with prognathism, HHAT with the complex Nivelon-Nivelon-Mabille Syndrome, MBOAT2 with chondrocyte differentiation, and ITGAV with chondrodystrophy), and one to calcium homeostasis (HPCAL1)." (PMID 36230363, 2022).
tumor (10 papers, 2004 to 2026). "As expected, liver-specific loss of Hpcal1 significantly facilitated tumorigenesis with evidence of increased liver weight, liver-body ratio, tumor number and liver tumor cell proliferation activity." (PMID 36438486, 2022). "Through the bioinformatics analysis, this study not only identified a tumor suppressor gene of CCA, CDH6, which has been confirmed by relevant basic studies, but also found a tumor‐promoting oncogene, HPCAL1, which was associated with poor prognosis of CCA and was confirmed by our validation cohort." (PMID 35645147, 2023). "Consistent with the observation that Hpcal1 deficiency resulted in dramatical increase of tumor growth above, this effect was partially reversed in tumors with simultaneous deficiency of Hpcal1 and Ruvbl1, considering that the tumor number was higher compared with that of Ruvbl1-deleted tumors." (PMID 36438486, 2022). "Given HPCAL1's established dual tumor-suppressive and oncogenic roles in other cancers, this study investigates its function in CRC to assess the therapeutic potential." (PMID 42091587, 2026). "In terms of tumor formation and development, HPCAL1 exhibits tumor-promoting activity in GBM by the activation of the embryonic developmental signals, especially the WNT-CTNNB1/β-catenin pathway." (PMID 36845736, 2023). "Compared with the wide type counterparts (WT), Hpcal1-/- mice had higher liver weight and liver-body ratio, and more tumor numbers." (PMID 36438486, 2022). "In this study, we have uncovered that HPCAL1 serves as an important negative regulator of de novo lipid and cholesterol biosynthesis and tumor progression in mice." (PMID 36438486, 2022). "The results of existing studies are inconsistent regarding the role of HPCAL1 in tumor growth." (PMID 40421217, 2025). "In addition, results of IHC analysis available from the HPA database showed that HPCAL1 was more highly expressed in CCA tumor tissues than in the normal bile duct." (PMID 35645147, 2023). "Analysis of data from 33 common cancers in the TCGA database revealed that the genes HLF, HPCAL1, and NUPR1 exhibit significant differential expression between tumor and normal tissues in LUAD and several other cancers." (PMID 40421217, 2025). "These variables were HPCAL1, CA19‐9, CA‐125, CEA, tumor number, tumor differentiation, vascular invasion, lymph node metastasis, and TNM stage." (PMID 35645147, 2023). "Strikingly, compared with control tumors, although Hpcal1-depleted mice had larger tumors, they showed higher sensitivity to AZD8055, with lower liver weight, liver-body ratio, tumor numbers and diminished Ki-67 staining." (PMID 36438486, 2022). "An obvious variation in the levels of HPCAL1 was detected in tumor samples (intensity scores from 0 for absent, 1 for weak, 2 for moderate, and 3 for strong)." (PMID 35645147, 2023). "Furthermore, results of the multivariate analysis suggested that HPCAL1, CA‐125, tumor number, and tumor vascular invasion were prognostic factors for RFS, whereas HPCAL1, CA19‐9, number of tumors, tumor vascular invasion, and TNM stage were prognostic factors for OS." (PMID 35645147, 2023). "High HPCAL1 expression was correlated with poor OS and RFS (criteria: good ≥3 years, living/relapse‐free, and poor ≤1 year, death/relapse prognosis) but was not significantly correlated with tumor histologic grade and clinical stage." (PMID 35645147, 2023).
cancer (9 papers, 2019 to 2026). A tumor composed of atypical neoplastic, often pleomorphic cells that invade other tissues. "The autophagic degradation of N-cadherin has recently been identified in cancer cell lines as a mechanism of ferroptosis, mediated by the selective cargo protein hippocalcin-like 1 (HPCAL1) and operating independently of GPX4 regulation or iron metabolism." (PMID 41304754, 2025). "Simultaneously, proliferation of cells was retarded in HPCAL1‐knockdown cancers according to WB of Ki67 and immunostaining of Brdu." (PMID 30843345, 2019). "As the markers in circulation have been most frequently used for the diagnosis of cancer and diagnosis before surgery, the presence of HPCAL1 in blood was examined." (PMID 30843345, 2019). "The average size of cancer was significantly smaller in HPCAL1‐knockdown group in comparison with that of the control group." (PMID 30843345, 2019). "Similar to the findings in cells, HPCAL1 transcription and translation were significantly promoted in the cancer tissues in comparison with those in non‐cancer tissues." (PMID 30843345, 2019). "Hippocalcin‐like 1 (HPCAL1) is involved in the development of several cancer types." (PMID 35645147, 2023). "Furthermore, the expression of the genes c‐Myc and β‐catenin was reduced in the HPCAL1‐knockdown cancer cells in comparison with that of the parent cancer cells." (PMID 30843345, 2019). "Moreover, studies on HPCAL1 have recently attracted increasing attention in cancer research." (PMID 35645147, 2023). "Western blot analysis confirmed significantly lower expression levels of HLF, NUPR1, and HPCAL1 in NCI-H1975 and A549 cancer cells (p < 0.05), suggesting these genes may be involved in the development of LUAD." (PMID 40421217, 2025). "In agreement with the previous observations by us and others 31, 52, despite being as a Ca2+ sensor, HPCAL1 interacted with RUVBL1 that was clearly not affected by Ca2+ concentration in cancers." (PMID 36438486, 2022).
infection (1 paper, 2019). The state of being infected such as from the introduction of a foreign agent such as serum, vaccine, antigenic substance or organism. "The A172 cells with elevated HPCAL1 expression were steadily exhausted via infection of two different shRNAs packing lentivirus (sh HPCAL1‐1 and sh HPCAL1‐2)." (PMID 30843345, 2019).
HPCAL1 also shares sentences with these, for which no sentence is quoted: asthma (2 papers); pancreatitis (2); autism (1); brain tumour (1); chronic kidney disease (1); cognitive decline (1); Cognitive impairment (1); diabetes (1); enteropathogenic Escherichia coli infection (1); Hypertension (1); intrahepatic cholangiocarcinoma (1); Jaundice (1); lung carcinoma (1); myocardial infarction (1); non-alcoholic fatty liver disease (1); prostate carcinoma (1); type 2 diabetes (1).